AFP (alpha fetoprotein)
Diseases named in the same sentence as AFP in open-access papers (continued):
Sharing a sentence is not in itself a finding about the gene and the disease.
tumor (continued). "Conventional prognostic models for HCC mainly involve integration of clinicopathological factors such as tumor size, number of lesions, microvascular invasion, and cirrhosis, supplemented by serum levels of certain single markers such as α−fetoprotein (AFP) and des−gamma carboxy−prothrombin (DCP)." (PMID 32760725, 2020). "Various tumor markers (AFP, CEA, CA125, CA199, and CA153) are normal." (PMID 32123165, 2020). "Apart from the common cancer types, sintilimab was involved in suppressing tumor progression on a KRAS positive patient with hepatoid adenocarcinoma (HAC), a sort of rare tumor secreting AFP with morphological similarities to HCC, and eventually achieved a 52-month OS." (PMID 33292551, 2020). "In this study, we performed a genome-wide analysis to identify differential alternative splicing (AS) events between HCCs with normal (< 20 ng/mL) and high (≥ 20 ng/mL) serum AFP levels using RNA-sequencing data for tumor tissues obtained from The Cancer Genome Atlas (TCGA) database." (PMID 33371894, 2020). "Moreover, tumor differentiation grade, alpha-fetoprotein level, tumor size, and tumor extension were all significantly associated with survival both before and after PSM." (PMID 32117759, 2020). "Patients with tumours larger than 3 cm that were AFP positive also had worse survival (P < 0.001)." (PMID 32117619, 2020). "Biologic tumor response evaluated with alpha-fetoprotein (AFP) serum level was available before index treatment and at follow-up in 43/97 (44%) patients with a mean baseline value of 330.6 ± 1026.6 (range 2–5700) ng/mL and matched follow-up values of 92.0 ± 241.8 (range 2–1200)." (PMID 33212917, 2020). "Moreover, many of the studies we included not only used BKK-1 as a tumour biomarker but also explored the diagnostic synergistic effects of DKK-1 and other markers, including the combination of AFP in HCC and the combination of CA19-9 in PC." (PMID 33193872, 2020). "There is growing evidence that intracellular AFP is involved in tumour growth." (PMID 33090723, 2020). "Besides, existing studies have also confirmed that AFP can promote the proliferation of tumour cells and inhibit the apoptosis induced by anti‐cancer drugs." (PMID 33090723, 2020). "The relatively short follow-up and the strong weight of tumor aggressiveness variables (AFP, and nodule number), or ASA score in survival models could also explain why the MELD score did not independently predict survival." (PMID 32013112, 2020). "Different factors have been shown to have a significant risk for early or late HCC recurrence including the high preoperative level of alpha fetoprotein (AFP), multiple tumors, large tumor size, macrovascular or microvascular invasion, and type of liver resection." (PMID 32426129, 2020). "In detail, larger tumor size (T2 vs. T0, HR = 8.53, p = 0.043; T3 vs. T0, HR 30.5, p = 0.001), vascular infiltration (HR = 11.39, p<0.001), and higher AFP values (log10-transformed; HR = 2.25 for a factor of 10, p<0.001) were significantly associated with HCC recurrence." (PMID 32614912, 2020). "The nomogram combined the significant prognostic factors, including Child-Pugh classification, status of intrahepatic tumor, presence of distant metastasis, location and number of metastatic abdominal lymph nodes(LNs), serum level of AFP, and the LN response to radiotherapy." (PMID 31528220, 2019). "However, it should be noted that relying solely on tumor burden and/or alpha-fetoprotein (AFP) cannot fully figure the biological aggressiveness of HCCs." (PMID 31142035, 2019). "The combination of exosomes and circulating miRNAs (miR-10b, miR-21, miR-122 and miR-200a) may serve as a promising tumor marker complementary to alpha-fetoprotein for early-stage HCC." (PMID 31656200, 2019).
tumor (continued). "Current studies demonstrate that DNA encoding epitope-optimized murine AFP and lentivector-mediated genetic immunization could induce potent AFP-specific CD8+ responses to generate a significant anti-tumor effect in autochthonous HCC model." (PMID 31500650, 2019). "Treatment exposure (HR = 2.191; 95% CI: 1.533–3.132; p < 0.001), tumor size (HR = 1.973; 95% CI: 1.230–3.164; p = 0.005), serum AFP level (HR = 1.752; 95% CI: 1.277–2.403; p = 0.001), and TNM stage (HR = 0.470; 95% CI: 0.319–2.504; p < 0.001), were independent factors for OS in HCC patients." (PMID 31164099, 2019). "Interestingly, we observed that MDT management was more beneficial under more complex clinical situations (poorer liver function, intermediate or advanced tumor stage or higher AFP levels)." (PMID 30640924, 2019). "While patients beyond Milan criteria but with AFP models of up to 2 points were recently shown to be at an increased, yet still acceptable, risk of tumor recurrence, this does not seem to apply to patients with intrahepatic dissemination." (PMID 31163668, 2019). "If the tumour is completely removed, the AFP value will gradually drop to normal." (PMID 31822277, 2019). "The AFP level increases physiologically during the first two years of life, but also in gastrointestinal or liver tissue tumours.The hCG value may be elevated due to other cancer types, marijuana use, etc.." (PMID 31652641, 2019). "However,The patients with largest nodule diameter of > 8 cm and serum AFP of > 1000 ng/mL will be categorized in the high-risk category, so LT should be excluded or neoadjuvant therapy and close surveillance until the tumor biology and morphology could be brought down to a safer level." (PMID 31752756, 2019). "Here, we found that NAP1L1 expression was significantly upregulated in HCC as compared to the adjacent non-tumor hepatocytes, and high NAP1L1 expression was significantly associated with aggressive clinicopathologic features (i.e., serum AFP levels, larger tumor size and late clinical stage)." (PMID 31516385, 2019). "Nevertheless, expansion of the conservative Milan criteria is currently in progress, most frequently on the basis of combining morphological and biological features, such as alpha-fetoprotein concentration, tumor differentiation, inflammatory markers, and response to neoadjuvant therapies." (PMID 31163668, 2019). "The equation was log AFP (ng/ml) = 0.66 + 0.74 × log tumor volume (cm3) (r = 0.451)." (PMID 30783140, 2019). "Furthermore, the expression of AFP was elevated in tumor tissues, while it was decreased in peritumoral tissues, which was similar to previous study." (PMID 30886700, 2019). "Tumor multiplicity and size were independent risk factors for female patients in BCLC stage 0-B, whereas tumor multiplicity, tumor size, HBV-DNA, hemoglobin, total bilirubin, and alpha-fetoprotein levels were independent risk factors for male patients in BCLC stage 0-B." (PMID 31413742, 2019). "Although the ability of AFP levels to predict HCC prognosis may be controversial, AFP has been shown to be affected by the condition of the tumor, including the tumor size and tumor multiplicity." (PMID 31413742, 2019). "It is possible that the sensitivity of the CSP score could be improved by adding factors related to the nutritional status (albumin or prealbumin) and tumor markers (CA125 or AFP)." (PMID 30849974, 2019). "After controlling for age, gender, AFP, tumor size, and tumor stage in multivariate Cox proportional regression model, Cluster2 patients still had significantly worse OS (p = 0.045, HR: 1.842 with 95% CI (1.012, 3.355)) and RFS (p = 0.041, HR: 1.657 with 95% CI (1.20, 2.692))." (PMID 31847435, 2019). "Considering abnormal elevation diagnostic value of AFP to HCC, it’s reasonable to understand that more quicker decrease ratio may present more thorough tumor clearance after surgery, and less possibility of recurrence." (PMID 31829979, 2019).
tumor (continued). "Such depletion in AFP by Adriamycin could be attributed to the ability of this drug to reduce tumor mass resulting in the decreased AFP synthesis by the cancer cells." (PMID 31653155, 2019). "ELISA assay was utilized to measure the levels of the tumor marker AFP (α-fetoprotein) and marker enzyme ALT (Alanine aminotransferase) which were markedly increased in the animal serum of control group (DEN-induced group) compared with that of the blank group (** p < 0.01)." (PMID 31801250, 2019). "Because both frequency of MDSC and serum levels of AFP were correlated to tumor volume, frequency of MDSC and serum levels of AFP may be related closely." (PMID 30783140, 2019). "Due to the presence of the AFP-producing tumor, we checked the AFP level after surgery." (PMID 29457212, 2019). "Notably, we found that mean AFP levels and tumor size were lowest in patients with haplogroup N9a and were top ranked in patients with haplogroup D5 and B5, respectively." (PMID 31629170, 2019). "We used serum AFP as a marker of tumor size, validated by bioluminescent imaging." (PMID 31636665, 2019). "However, the overall efficiency is still unsatisfactory, especially in HCC patients with low AFP level or small-size tumor." (PMID 31737122, 2019). "The tumor size, tumor number, AFP level, vascular invasion, Child–Pugh score, objective response after TACE, and NLR, selected as predictors of overall survival (OS) via multivariate Cox’s regression model, were incorporated into a 14-point risk prediction model (SNAVCORN score)." (PMID 30974843, 2019). "Serum AFP level at presentation correlates with tumor size and extent." (PMID 31829979, 2019). "Due to the excessive missing information for tumor size, tumor differentiation and AFP, only “Author”, “Year of publication”, “Country”, “Number of patients” (NP), “Number of significant genes” (NG),”Clinical tissue” (Tissue), “Contain adjacent tissue” (C&A) and “Etiology” were included." (PMID 31771612, 2019). "Alpha-fetoprotein (AFP) levels are considered to be indicators of tumor activity in HCC patients." (PMID 31413742, 2019). "Tumor size, type of surgery and AFP level also had a significant effect on DSS." (PMID 30863723, 2019). "The result showed that the serum level of AFP had moderately positive correlation to tumor volume." (PMID 30783140, 2019). "Given that its weight may be larger than that of AFP, but less than that of tumor size or number, PIVKA‐II level might be used as an ancillary method to complement conventional tumor factors for delicate prognostification." (PMID 31290618, 2019). "In a HuH6 xenograft mouse model (80 mg/kg/day aprepitant for 24 days), reduction of tumor growth (reduced tumor volume and weight) was reported along with a lowered tumor-specific alpha-fetoprotein (a marker of HB) serum level and a decreased number of Ki-67 positive cells." (PMID 31466222, 2019). "Notably, the incidence of serum Wnt3a was 81.4% in HCC patients with AFP level less than 20 μg/L (48/59), 92.6% in the cases with tumor size less than 3.0 cm (75/81), and up to 93.9% when Wnt3a plus AFP combination." (PMID 31737122, 2019). "Lower AFP at the time of LT was another evidence of good tumour behaviour in the PDS group." (PMID 31316165, 2019). "It is thus of imperative significance to search for surrogate tumor markers for normal AFP-HCC." (PMID 31635078, 2019). "In addition, a decreased number of tumour nodules and significantly reduced levels of AFP reflected lower tumour production rates." (PMID 31836811, 2019). "Although it has a limitation that MVI cannot be examined preoperatively, our data suggested that tumour number and size on the imaging study along with AFP could predict PDS." (PMID 31316165, 2019). "Moreover, the targetable signalling pathways IGF1R, NOTCH and mTOR were upregulated in AFP-high tumours." (PMID 31285588, 2019).
tumor (continued). "According to performed analyses adjusted for the confounding effects of differences in baseline characteristics, assessment of CPR to neoadjuvant treatment does not improve the capability of selection criteria combining morphologic features with AFP to predict tumor recurrence." (PMID 31520204, 2019). "Laboratory findings, including tumor markers and serum levels of AFP and β-HCG, were normal." (PMID 30882650, 2019). "Tumour markers including AFP, CA 19-9 and CEA were all normal." (PMID 30731302, 2019). "In a cohort of 217 resected HCCs, 75% of tumors expressed PD-L1, and PD-L1 expression was associated with aggressive tumor features (high alpha-fetoprotein (AFP) levels, satellite nodules, poor differentiation, vascular invasion)." (PMID 31892230, 2019). "Consequently, we diagnosed the tumor to have metastasized from the AFP-GC resected 15 years previously." (PMID 31264022, 2019). "Immunostaining showed tumor cells strongly positive for AFP." (PMID 31281709, 2019). "In liver transplantation, AFP is a risk factor of tumor recurrence after liver transplantation and high level of AFP is even not suitable to undergo liver transplantation." (PMID 30783140, 2019). "In addition, elevated PLR correlated closely with AFP >300 (P 0.07) and tumor presence on explant (P 0.08) which are well-established predictors of survival." (PMID 31737675, 2019). "We also found that low expression level of CTC‐297N7.9 is closely associated with the clinicopathological characteristics indicating poor prognosis of HCC patients, such as high serum AFP level, advanced tumor stage, poor differentiation, and vascular invasion." (PMID 31674731, 2019). "We found that elevated preoperative serum CA125 concentrations were associated with larger tumor diameter and poor prognosis among patients, although there was no significant increase in preoperative serum AFP concentrations." (PMID 31662990, 2019). "Compared to the patients who had a good respond to chemotherapy, the decrease in serum AFP was slower in patients with a worse response, confirming that active tumour cells remained, which may lead to recurrence after chemotherapy." (PMID 31822277, 2019). "Serum AFP is one of several tumor markers that become elevated where certain cancers are present." (PMID 30755785, 2019). "Univariable analysis showed that the poor prognostic factors for OS were older age, tumour size, macroscopic multiple tumours, poor differentiation, microvascular invasion, microscopic intrahepatic metastases, AFP level, DCP level, high NLR and PLR, and low LMR." (PMID 31388642, 2019). "Our result was consistent with this hypothesis, by revealing that the higher the HAS cell component percentage in a tumour, the more is the AFP secreted by the tumour." (PMID 30989433, 2019). "In conclusion, elevated preoperative serum CA125 predicted larger tumor diameter in patients with HCC with AFP ≤200 ng/mL and may help in the assessment of prognosis after surgery." (PMID 31662990, 2019). "Tumor markers of AFP, beta hCG LDH, and CA125 were measured in all patients." (PMID 31897390, 2019). "All adverse events experienced by the patients were recorded; the changes in tumor biomarkers [AFP, CA 19-9, circulating tumor cells (CTCs)], lymphocyte number and function, quality of life, clinical response, progression-free survival (PFS) and overall survival (OS) were assessed." (PMID 30151798, 2019). "Laboratory examinations including the routine blood test, liver function tests, coagulation analysis, urinalysis, and tumor biomarker tests such as alpha fetoprotein(AFP), carcinoembryonic antigen(CEA) and Human Chorionic Gonadotropin(HCG) were showing no abnormality." (PMID 31711457, 2019). "We then analyzed preoperative tumor markers level of AFP, CA19-9, and CEA." (PMID 31205886, 2019). "Age, male sex, Non-B&C, maximum tumor diameter, AFP level, and CTP class were independent risk factors for OS." (PMID 31048923, 2019).
tumor (continued). "Specifically, AFP-high tumours displayed significant activation of VEGF signalling (p < 0.001), which might provide the rationale for the reported benefit of ramucirumab in this subgroup of patients." (PMID 31285588, 2019). "In this study, serum AFP level had moderately positive correlation to tumor volume and MDSC." (PMID 30783140, 2019). "Finally, the multivariate analysis by Cox regression showed that AFP decreased by less than 60% and tumour size decreased by less than 50% after neoadjuvant chemotherapy were significant independent prognostic risk factors for the 3-year RFS rate." (PMID 31822277, 2019). "After adjusted for other confounding factors, ALDH2 “GG” genotype (P = 0.019), microvascular invasion (P < 0.001), macrovascular invasion (P = 0.006), larger tumor size (P = 0.017), and higher AFP (P = 0.003) remained as independent predictors for a shorter time-to-distant metastasis." (PMID 31737110, 2019). "Tumor burden by bioluminescence and serum AFP concentration was highly correlated in our model." (PMID 31636665, 2019). "We hypothesized that tumours’ sensitivity to chemotherapy results in a significant decrease in serum AFP before surgery." (PMID 31822277, 2019). "The performance of ΔMoRAL in predicting OS was significantly better than the performances of initial respective serum tumor markers, baseline MoRAL score, and changes in serum tumor markers, except for the baseline AFP level, in both the training and hospital validation cohorts (all p < 0.05)." (PMID 31689972, 2019). "Association of the extent of marker level elevation with tumour size was found for AFP in the nonseminoma group and for bHCG and LDH in the entire GCT group." (PMID 31275973, 2019). "Taking all the results of assisted examinations into consideration, we did not consider that the increased AFP level was caused by tumor recurrence." (PMID 31836006, 2019). "The “Non-TT” variant type was associated with lower cumulative incidence of distant metastasis in the patients with tumor grade≦3 (HR 0.599, 95% CI 0.367–0.979, P = 0.041), microvascular invasion (HR 0.500, 95% CI 0.257–0.975, P = 0.042) and AFP > 26.5 ng/mL (HR 0.538; 95%CI 0.296–0.979, P = 0.043)." (PMID 31805979, 2019). "In contrast, tumor size, response to local ablative treatment, alpha-fetoprotein (AFP), C-reactive protein, and microvascular invasion may better correlate with recurrence." (PMID 31737675, 2019). "Furthermore, the AFP level ≥400 ng/ml, tumor number ≥2, tumor size ≥5 cm, distant metastasis, major and microvascular invasion and positive margin influenced the HR either." (PMID 31567946, 2019). "Multivariable analysis presented that tumor number (hazard ratio (HR)=1.238, 95% CI: 1.095‐1.400, P = 0.002), alpha‐fetoprotein (AFP) (HR = 1.485, 95% CI:1.237‐1.783, P < 0.001), and the type of initial treatment (HR = 1.497, 95% CI: 1.328‐1.688, P < 0.001) was the significant factors for OS." (PMID 30864247, 2019). "This could be seen when the tumor markers as alpha fetoprotein, carcino-embryonic antigen and human gonadotrophin are elevated." (PMID 30522078, 2019). "Alpha-fetoprotein (AFP) is one of the major tumor markers for HCC used in clinics and are specific antigens presented on the cell surface; thus, AFP is used for molecular targeting of CAR-T-cells for HCC (NCT03971747) in both ex vivo gene therapy and cancer vaccination (NCT00005629 and NCT03971747)." (PMID 31769427, 2019). "Finally, seven essential variables including tumor size, tumor number, AFP level, PIVKA‐II level, lymphocyte count, albumin level, and presence of ascites were identified as prognostic factors with statistical significance." (PMID 31290618, 2019).